SOD1 (superoxide dismutase 1)
Diseases named in the same sentence as SOD1 in open-access papers (continued):
Sharing a sentence is not in itself a finding about the gene and the disease.
amyotrophic lateral sclerosis (continued). "Amyotrophic lateral sclerosis (ALS) is a fatal neurodegenerative disease with familial inheritance (fALS) in 5% to 10% of cases; 25% of those are caused by mutations in the superoxide dismutase 1 (SOD1) protein." (PMID 24312616, 2013). "In the superoxide dismutase-1 mutant rat model of amyotrophic lateral sclerosis, IgG is also reported in the lumbar spinal cord and cortex, although interestingly at the pre-symptomatic stage prior to changes in occludin and increased penetration of Evans Blue dye." (PMID 22713725, 2012). "In addition to these contusion models high scores were for a murine SOD1(G93A) mutant model of Amyotrophic lateral sclerosis (ALS) (GEO accession GSE18597) and a murine model of prion disease (GEO accession GSE23182)." (PMID 22233519, 2012). "There is abundant evidence for an early and profound impairment of neuromuscular transmission in amyotrophic lateral sclerosis, and we showed previously that mutant forms of superoxide dismutase 1 (SOD1) alter the morphology and survival of hESC-derived MNs in vitro." (PMID 22574134, 2012). "In the 1990s, the scientific community focused their studies on the genetic and biochemical characterization of SOD1, demonstrating that SOD1 plays an important role in diseases as heart failure, cancer, diabetes, Down's syndrome, and amyotrophic lateral sclerosis." (PMID 21603028, 2011). "For instance, several hundred mutations in the SOD1 protein were shown to result in aggregates associated with amyotrophic lateral sclerosis in humans; also, non-natural peptides have been used to induce cytotoxic aggregates of GFP in C. elegans." (PMID 20920270, 2010). "Neuronal cells expressing a SOD1 mutant frequently encountered in familial cases of amyotrophic lateral sclerosis are more vulnerable to the direct action of the bacterial hemolysin pneumolysin and to the attack of activated immune cells than neuronal cells expressing wild-type SOD1." (PMID 17997855, 2007). "In an in-vitro model of amyotrophic lateral sclerosis we showed that SH-SY5Y neuroblastoma cells transfected with the G93A mutant of SOD1 typical for familial ALS (G93A-SOD1) are more vulnerable to infectious stimuli than neuroblastoma cells overexpressing normal SOD1." (PMID 17997855, 2007). "In amyotrophic lateral sclerosis (ALS) mitochondrial dysfunction and apoptotic cell death due to mitochondrial SOD1 enzyme aggregation has been reported." (PMID 41502474, 2026). "PURPOSE: Misfolded superoxide dismutase-1 (mSOD1) is an abnormal protein observed in amyotrophic lateral sclerosis (ALS) and constitutes a therapeutic target." (PMID 41872337, 2026). "Using the sod-1 A4VM amyotrophic lateral sclerosis (ALS) model in Caenorhabditis elegans, we investigated the protective effects of the probiotic Enterococcus faecium against oxidative stress-induced neurodegeneration." (PMID 41616251, 2026). "The paper reports the results of a computational study on compounds capable of inhibiting the prion-like infection mechanism of superoxide dismutase-1 (SOD1) mutants, which are the basis of amyotrophic lateral sclerosis (ALS)." (PMID 40429802, 2025). "FUS and SOD1, for example, are central to certain forms of amyotrophic lateral sclerosis (ALS) and frontotemporal lobar degeneration (FTLD)." (PMID 41303689, 2025). "Values for protein and superoxide dismutase‐1 (SOD1) activity in controls and amyotrophic lateral sclerosis (ALS) patients." (PMID 40548824, 2025). "Calcium dysregulation, caused by pathological activation of ryanodine receptors, contributes to motor neuron degeneration, motor dysfunction, and muscle weakness in SOD1-G93A transgenic amyotrophic lateral sclerosis (ALS) mice." (PMID 40501612, 2025). "Nusinersen treatment was a breakthrough intervention in the recessive disease spinal muscular atrophy, and superoxide dismutase 1 (SOD1) amyotrophic lateral sclerosis (ALS) seems to be the paradigm disease in dominant degenerative diseases." (PMID 39845577, 2025).
amyotrophic lateral sclerosis (continued). "In the context of amyotrophic lateral sclerosis (ALS), lines expressing mutant forms of SOD1, TDP-43, or FUS recapitulate motor neuron degeneration and neuromuscular junction damage, allowing real-time imaging of disease progression and therapeutic testing." (PMID 41302176, 2025). "The proteins implicated in amyotrophic lateral sclerosis (ALS), including TAR DNA-binding protein 43 (TDP-43), fused in sarcoma (FUS), superoxide dismutase 1 (SOD1), and chromosome 9 open reading frame 72 (C9orf72) repeat peptides, are also related to the DDR." (PMID 39063148, 2024). "ASOs have seen recent success outside the cancer field, with the SOD1 targeting ASO Tofersen recently gaining US FDA approval for the treatment of SOD1-positive amyotrophic lateral sclerosis (ALS)." (PMID 39062685, 2024). "Independent of infection, in a model of misfolded mutant Superoxide dismutase (SOD1)-driven amyotrophic lateral sclerosis (ALS), damaged mitochondria-released mtDNA and mt(DNA/RNA) hybrids activated the cGAS-STING and DDX41-STING pathways, respectively." (PMID 39185415, 2024). "The involvement of SOD1 in the pathogenesis of various diseases, such as familial amyotrophic lateral sclerosis (ALS), has been well documented." (PMID 39290254, 2024). "Our study investigated the therapeutic potential of OKN-007 in the SOD1 G93A mouse model of amyotrophic lateral sclerosis (ALS)." (PMID 39633896, 2024). "For instance, exosomes from apoptotic neurons containing misfolded mutant SOD1 can trigger neuronal death and contribute to amyotrophic lateral sclerosis (ALS)." (PMID 38424607, 2024). "Our study aimed to investigate the potential therapeutic effects of OKN-007 on the progression of amyotrophic lateral sclerosis (ALS) using the SOD1 G93A mutant mouse model." (PMID 39633896, 2024). "The role of SOD1 in neuroinflammation was mainly studied in an amyotrophic lateral sclerosis (ALS) model in mutant mice with hyperactivation of interferon pathways." (PMID 39061948, 2024). "Additionally, significant benefits were observed with the intrathecal administration of a miR-124-depleted secretome in a mouse model of amyotrophic lateral sclerosis (SOD1-G93A), preventing neurodegeneration and glial dysfunction, along with a marked delay in disease progression." (PMID 38474035, 2024). "Pathogenic variants in the Cu/Zn superoxide dismutase (SOD1) gene can be detected in approximately 2% of sporadic and 11% of familial amyotrophic lateral sclerosis (ALS) patients in Europe." (PMID 39141064, 2024). "In amyotrophic lateral sclerosis (ALS) postmortem tissue and the SOD1 mouse model at mid-disease, death of hypoglossal motor neurons (XII MNs) is evident." (PMID 39119557, 2024). "The Drosophila Amyotrophic Lateral Sclerosis (ALS) model expresses mutant forms of genes associated with ALS, such as superoxide dismutase 1 (SOD1) and TAR DNA-binding protein 43 (TDP-43), have contributed to our understanding of ALS pathogenesis." (PMID 39590469, 2024). "In addition, it is useful to compare these patients to sporadic patients without amyotrophic lateral sclerosis-related gene mutations and with patients carrying other genetic mutations such as SOD1 in order to identify mutation-specific characteristics." (PMID 37006326, 2023). "For example, supplementation of S-Adenosyl methionine (SAM) in a transgenic mouse model (SOD1-G93A) of amyotrophic lateral sclerosis (ALS) delayed the onset of motor neuron pathology." (PMID 36590248, 2023). "Mutations in superoxide dismutase 1 (SOD1) result in misfolding and aggregation of the protein, causing neurodegenerative amyotrophic lateral sclerosis (ALS)." (PMID 36672132, 2023). "P2RY12 was decreased in the spinal cord of mutant SOD1 mice that mimicked amyotrophic lateral sclerosis pathology, although Iba-1-positive microglia were increased, indicating that the loss of microglia homeostatic genes might be involved in microglial dysfunction in neurodegenerative diseases." (PMID 37396924, 2023).
amyotrophic lateral sclerosis (continued). "Around three decades ago, the identification of the first SOD1 mutation in a group of familial amyotrophic lateral sclerosis (ALS) patients changed the perception of SOD1 being a protective antioxidant to the culprit in ALS." (PMID 36672132, 2023). "In most cases of amyotrophic lateral sclerosis, there is no family history associated, but in about 10% of cases, a dominantly inherited autosomal mutation occurs in distinct genes, such as in superoxide dismutase 1 (SOD1), C9orf72, and TAR DNA-binding protein 43 (TDP-43) genes." (PMID 37259454, 2023). "Tominersen is an ASO targeting the huntingtin mRNA of Huntington’s disease (HD), and tofersen is an ASO targeting the superoxide dismutase 1 (SOD1) mRNA of SOD1 dependent amyotrophic lateral sclerosis (ALS)." (PMID 35745855, 2022). "SOD1 was also upregulated in amyotrophic lateral sclerosis (ALS) patients, which indicates potential connections between irradiation and neurodegenerative disorders." (PMID 36551187, 2022). "SOD1 is involved in the pathogenesis of amyotrophic lateral sclerosis (ALS), as in the case of 20–25% of the familial ALS (fALS) patients the SOD1 protein is mutated." (PMID 35630637, 2022). "In the SOD1 transgenic mouse model of Amyotrophic Lateral Sclerosis (ALS), reactive and hypertrophic astrocytes upregulate GFAP expression in the spinal cord." (PMID 35535566, 2022). "Many studies have been focused on the role of aberrant metal homeostasis and binding in the aggregation process of SOD1 that has been shown to trigger SOD1 toxic deposition in amyotrophic lateral sclerosis (ALS)." (PMID 35892326, 2022). "Abnormal protein aggregation of mutant Cu/Zn superoxide dismutase 1 (SOD1) was the main pathological change of amyotrophic lateral sclerosis (ALS)." (PMID 35531069, 2022). "In humans, we can see the importance of the protein SOD1 in the case of amyotrophic lateral sclerosis (ALS)." (PMID 36363706, 2022). "For example, activation is induced in AD via Aβ, in Diabetes type II (T2D) via IAPP, in PD via α-synuclein and in amyotrophic lateral sclerosis (ALS) through SOD1." (PMID 35877764, 2022). "Cu, Zn-superoxide dismutase (SOD1, a 32 kDa homodimeric protein) was the first protein found to be closely related to amyotrophic lateral sclerosis (ALS)." (PMID 36364128, 2022). "In 1993, variants in the gene superoxide dismutase 1 (SOD1, [NM_000454]) were identified as a causal factor in people with amyotrophic lateral sclerosis (ALS), through analysis of 13 different families with 11 different SOD1 missense mutations." (PMID 36371497, 2022). "Neural tissues or sera from amyotrophic lateral sclerosis (ALS) patients and transgenic mice expressing mutant SOD1 have been reported to exhibit increased deoxyribonucleic acid (DNA) damage and lipid peroxidation." (PMID 34412689, 2021). "In another study, AAV-mediated intein-split delivery of CBE was implemented to disable the mutant SOD1 allele in SOD1G93A mice, which markedly slowed down the progression of amyotrophic lateral sclerosis (ALS) disease and prolonged survival." (PMID 33594520, 2021). "Metallation status of human Cu/Zn superoxide dismutase 1 (SOD1) plays a pivotal role in the pathogenesis of amyotrophic lateral sclerosis (ALS)." (PMID 34540798, 2021). "Another example is ASO developed to target superoxide dismutase 1 (SOD1) for the treatment of amyotrophic lateral sclerosis (ALS)." (PMID 33513969, 2021). "RNF19A also appears to play a role in familial amyotrophic lateral sclerosis (ALS) by ubiquitylating mutant superoxide dismutase (SOD-1) proteins and promoting their degradation, thereby contributing to the protection of surviving motor neurons." (PMID 34864818, 2021). "Recently, the CARP RD2RD2 (ptlhthnrrrrrptlhthnrrrrr; +10.4 charge) was investigated as a potential therapeutic candidate for amyotrophic lateral sclerosis (ALS) in a mouse model of mutant superoxide dismutase 1 (SOD1) expression." (PMID 34776866, 2021).
amyotrophic lateral sclerosis (continued). "This scenario is best supported by a series of SOD1 mutant studies, initially designed for the study of amyotrophic lateral sclerosis (ALS)." (PMID 34445751, 2021). "Moreover, unlike SOD2(-/-) mice, homozygous mutations in the SOD1 gene are not lethal; still, SOD1(-/-) mice exhibit subtle defects, including Amyotrophic Lateral Sclerosis (ALS), retinal dysfunction, and muscle atrophy." (PMID 33613826, 2021). "For example, in several SOD1 mutant mouse models, which are widely used to study pathology of amyotrophic lateral sclerosis (ALS), alterations in SC activity and morphology precede denervation of NMJs and impede NMJ repair." (PMID 34943800, 2021). "Superoxide dismutase 1 (SOD1) is known to be involved in the pathogenesis of Amyotrophic Lateral Sclerosis (ALS) and is therefore considered to be an important ALS drug target." (PMID 33635895, 2021). "For example, deficiencies in the cytosolic isoform of SOD (i.e., SOD1) have long been revered as key contributors to age- and disease-related functional dependencies, with the most-common demonstration of this seen in mouse models of amyotrophic lateral sclerosis (ALS)." (PMID 34686594, 2021). "Here we show that CRISPR/Cas9-mediated genome editing in two distinct SOD1-amyotrophic lateral sclerosis (ALS) transgenic mouse models prevented the development of ALS-like disease and pathology." (PMID 33767386, 2021). "The rise in LC3-II was greater in microglial cells from the SOD1-G93A mouse model of amyotrophic lateral sclerosis (ALS) than the wild type, and peaked 15 min after agonist presentation." (PMID 33790743, 2021). "Superoxide dismutase 1 (SOD1) is a predominantly cytosolic protein, with a mutant SOD1, associated with amyotrophic lateral sclerosis (ALS), found in mitochondria-rich fractions of cells." (PMID 33114780, 2020). "It has been demonstrated that curcumin regulates the early aggregation phases of reduced superoxide dismutase 1 (SOD1), one of the main proteins associated with Amyotrophic Lateral Sclerosis (ALS), leading to the production of non-fibrillar smaller and less toxic aggregates." (PMID 33217959, 2020). "One of the pathogenic aggregates identified in amyotrophic lateral sclerosis (ALS), namely superoxide dismutase 1 (SOD1), is internalised by macropinocytosis by both NSC-34 cells, a mouse motor neuron-like cell line, and human iPSC-derived motor neurons." (PMID 32756454, 2020). "Importantly, the SOD1 pathogenic mutants G85R and G93A are enriched in the IMS, which may contribute to mitochondrial dysfunction in amyotrophic lateral sclerosis (ALS)." (PMID 32779864, 2020). "The diagnosis of amyotrophic lateral sclerosis (ALS) can only be fully confirmed by the post mortem detection of ALS-associated protein inclusions such as TDP-43 and SOD1." (PMID 31616242, 2019). "In vivo, high expression levels of nucleotide-binding oligomerization domain-like receptor protein (NLRP) 3 related to the neuroinflammatory response has been found in astrocytes of SOD1 mice and in Amyotrophic lateral sclerosis (ALS) patients." (PMID 31749689, 2019). "Impaired interactions between Calcineurin (Cn) and (Cu/Zn) superoxide dismutase (SOD1) are suspected to be responsible for the formation of hyperphosphorylated protein aggregation in amyotrophic lateral sclerosis (ALS)." (PMID 29299811, 2019). "Both familial and sporadic Amyotrophic Lateral Sclerosis (ALS) is associated with cytosolic aggregation of proteins, most frequently TDP-43, with FUS and SOD1 seen in some familial cases." (PMID 31783880, 2019). "In Amyotrophic Lateral Sclerosis (ALS), the abundant protein superoxide dismutase (SOD1) or the TAR-DNA binding protein TDP-43 can aggregate in motor neurons." (PMID 30401824, 2018). "Amyotrophic lateral sclerosis (ALS) involves the abnormal posttranslational modifications and fibrillization of copper, zinc superoxide dismutase (SOD1) and TDP-43." (PMID 29358575, 2018).
amyotrophic lateral sclerosis (continued). "In SOD1 G93A mice, a mouse model for amyotrophic lateral sclerosis (ALS), boosting retrograde signaling by modestly increasing MuSK gene expression decreases the rate and extent of denervation and improves motor performance." (PMID 29415504, 2018). "LC3 is the processing protein in the spinal cord and activates motor neurons (MNs) of Zn-superoxide dismutase (SOD1) mice, suggesting a potential role of autophagy in the pathogenesis of amyotrophic lateral sclerosis (ALS)." (PMID 29738493, 2018). "Studies have shown that mitochondrial structure is altered in the motor neurons of mutant SOD1 mice, a model of Amyotrophic Lateral Sclerosis (ALS)." (PMID 29267205, 2017). "G-CSF attenuated apoptotic death and improved the functional outcome in experimental models of spinal cord injury and motor function and life expectancy in the SOD1 (G93A) transgenic mouse, a rodent model for amyotrophic lateral sclerosis (ALS)." (PMID 29362521, 2017). "Meanwhile, the accumulation of mutant SOD1 in the ER may also induce amyotrophic lateral sclerosis." (PMID 28208696, 2017). "Among the most prominent examples are the Aβ peptides in Alzheimer (AD), α-synuclein in Parkinson (PD), prion protein in prion deposits typical of Creutzfeldt–Jakob disease (CJD), and superoxide dismutase-1 (SOD-1) in amyotrophic lateral sclerosis (ALS)." (PMID 28538697, 2017). "A recent study showed a significant up-regulation of MEF2C and MEF2D mRNA levels in both sporadic and SOD1+ amyotrophic lateral sclerosis (ALS) patients detected by gene expression analysis, and a down-regulation of their targets, BDNF, KLF6, and RUFY3." (PMID 29340119, 2017). "Previously, we found that human Cu, Zn-superoxide dismutase (SOD1) is S-acylated (palmitoylated) in vitro and in amyotrophic lateral sclerosis (ALS) mouse models, and that S-acylation increased for ALS-causing SOD1 mutants relative to wild type." (PMID 28120938, 2017). "A proportion of Amyotrophic lateral sclerosis (ALS) cases result from impaired mutant superoxide dismutase-1 (SOD1) maturation." (PMID 27282955, 2016). "Therefore, it is tempting to speculate thatH2S-induced persulfide formation on SOD1 may play a role infamilial amyotrophic lateral sclerosis by influencing the aggregation ofSOD134." (PMID 27411966, 2016). "In humans, SOD1 mutations are linked to familial amyotrophic lateral sclerosis (ALS), and post-translational modification (PTM) of wild-type SOD1 has been associated with sporadic ALS." (PMID 28066183, 2016). "Similar models of induced protein aggregation have also been described for PD (inoculation of α-synuclein aggregates), amyotrophic lateral sclerosis (ALS) (inoculation of misfolded SOD-1) and tauopathy (inoculation of filamentous tau)." (PMID 27376534, 2016). "Amyotrophic lateral sclerosis (ALS) is a progressive neurodegenerative disease involving cytotoxic conformations of Cu, Zn superoxide dismutase (SOD1)." (PMID 26099300, 2015). "In Sod1 mutant mice modelling amyotrophic lateral sclerosis (ALS), extracellular free-floating mitochondria have been described in the brainstem." (PMID 26550569, 2015). "Some success with miR-155 targeting has been reported in the SOD1 mouse, a model for amyotrophic lateral sclerosis (ALS)." (PMID 26834738, 2015). "Numerous sub-cellular through system-level disturbances have been identified in over 1300 articles examining the superoxide dismutase-1 guanine 93 to alanine (SOD1-G93A) transgenic mouse amyotrophic lateral sclerosis (ALS) pathophysiology." (PMID 25998063, 2015). "Taken together, these data identify OXR1 as the first neuron-specific antioxidant modulator of pathogenesis and disease progression in SOD1-mediated amyotrophic lateral sclerosis, and suggest that OXR1 may serve as a novel target for future therapeutic strategies." (PMID 25753484, 2015).